STAT3 (signal transducer and activator of transcription 3)
Diseases named in the same sentence as STAT3 in open-access papers (continued):
Sharing a sentence is not in itself a finding about the gene and the disease.
cancer (continued). "For example, STAT3 is cleaved in a caspase-dependent manner in cancer cells treated with staurosporine, resulting in inactivation of STAT3." (PMID 40875771, 2025). "Ongoing studies are also assessing the advantage of combined therapy of BRD4 inhibitors and Stat3 blockers or BRD4 inhibitors with chemotherapy over monotherapy in suppressing cancer growth." (PMID 41311847, 2025). "Given the critical role of STAT3 in cancer development and progression, targeting this pathway has emerged as a promising therapeutic strategy." (PMID 40860906, 2025). "This dual role of STAT3, the induction of positive regulators and suppression of inhibitors, renders it a central player in promoting cell division in cancer cells." (PMID 40278288, 2025). "To date, only a limited number of STAT3 inhibitors have been approved by the USFDA for cancer treatment, and several concerns persist." (PMID 40166646, 2025). "It inhibits STAT3 phosphorylation, DNA binding, and transcriptional activity, which are essential for cancer cell growth and migration." (PMID 40575656, 2025). "Transcriptomic analyses also highlight STAT3's involvement in muscle atrophy during cancer cachexia." (PMID 39764565, 2025). "STAT3 enhances cell adhesion by upregulating molecules such as E-selectin and P-selectin in endothelial cells, thereby facilitating cancer cell invasion and metastasis." (PMID 39781359, 2025). "Collectively, these mechanisms highlight STAT3’s central role in promoting muscle atrophy through enhanced proteolysis, dysregulated autophagy, and impaired regenerative capacity, key drivers of cancer cachexia progression." (PMID 40704145, 2025). "A recent study has shown that MYC binds to promoters, invades distal enhancers, and co-occupies them with cancer-type-specific TFs, such as ER and STAT3." (PMID 40032852, 2025). "In this experimental model, ILF2-ILF3 binding to PD-L1 preceded and induced STAT3 phosphorylation, favoring cancer cell progression." (PMID 40427133, 2025). "Chronic stress and cancer induce a systemic pro‐inflammatory state through common signaling pathways such as NF‐kB, STAT3, and mTOR, promoting tumor growth and metastasis while also contributing to neuroinflammation." (PMID 40387308, 2025). "For instance, HF can inhibit the pro-survival AKT/STAT3 signaling in cancer cells to promote death, yet it activates the SIX4/AKT/STAT3 axis to protect hepatocytes from injury." (PMID 41511301, 2025). "By upregulating immune checkpoint proteins like PD-L1, STAT3 allows cancer cells to escape immune surveillance, which is a major factor in therapeutic resistance, particularly in TNBC." (PMID 41463071, 2025). "In total, these findings underscore the therapeutic potential of STAT3-targeted interventions in cancer cachexia." (PMID 40704145, 2025). "Intriguingly, the overexpression of a constitutively active STAT3 mutant (STAT3-C) was shown to partially reverse OC’s anti-cancer effects, underscoring the critical contribution of STAT3 inhibition to its mechanism of action." (PMID 40564985, 2025). "A growing body of evidence from both preclinical and clinical studies indicates that multimodal exercise interventions can effectively mitigate STAT3-driven muscle atrophy in cancer cachexia by modulating inflammatory signaling and enhancing anabolic pathways." (PMID 40704145, 2025). "Previous studies have shown that dysregulation of BLC2, ALB, and STAT3 plays a significant role in cancer-related fatigue by driving systemic inflammation and metabolic alterations." (PMID 40435272, 2025). "In some tumors, IL-32 contributes to cancer progression by modulating key signaling pathways, including NF-κB, STAT3, and MAPK." (PMID 41181127, 2025).
cancer (continued). "This STAT3 ODN-decoy has been tested in various cancer cell lines, where it displayed promising effects, such as apoptosis induction, diminution of cancer cell proliferation, and reduction in Bcl-xL and cyclin D1 gene expression." (PMID 41031165, 2025). "A study synthesized (E)‐2‐methoxy‐4‐(3‐(4‐methoxyphenyl) prop‐1‐en‐1‐yl) phenol (MMPP), a novel small molecule that effectively inhibits cancer progression by targeting the STAT3 DBD." (PMID 40166646, 2025). "It directly binds to STAT3, preventing its activation, and induces G1 cell cycle arrest and apoptosis in cancer cells." (PMID 40231344, 2025). "IL-6 activates downstream targets via phosphorylation of ERK1/2 (p-ERK1/2) and STAT3 (p-STAT3) in cancer cells." (PMID 39858048, 2025). "Recent studies demonstrated that morusin can inhibit the activation of NF-κB and activators of STAT-3 in cancer cells, including prostate, pancreatic, and liver." (PMID 41322309, 2025). "The direct downstream genes of STAT3, including FOXM1, NANOG, TWIST, SLUG, and ZEB1, are linked to cancer stemness and EMT." (PMID 39940889, 2025). "The constitutive activation of STAT3 has been observed in numerous types of cancers, such as breast, colon, pancreatic, lung, and ovarian cancers, as well as hematological malignancies like lymphomas and leukemias." (PMID 40860906, 2025). "The biological effects of these STAT3 inhibitors on human cancer cells were assessed via simulation." (PMID 40061959, 2025). "The mechanism of iNOS overexpression in cancer is complex and involves activation of the NF-κB and STAT3 signaling pathways, which are often overactive in cancer cells and promote the expression of pro-inflammatory and proliferative genes." (PMID 40649317, 2025). "While most of these genes’ precise role in regulating STAT3 is not well-defined, it was shown that tyrosine phosphatase PTPRD can dephosphorylate STAT3 in cancer cells." (PMID 39985075, 2025). "Recent studies have shown that MCP1 signaling can promote cancer cell migration and invasion through the activation of STAT3 in various cancer cells." (PMID 40430040, 2025). "By targeting STAT3, these downstream oncogenic pathways can be suppressed, potentially reducing cell proliferation and inducing apoptosis across various cancer types." (PMID 40075607, 2025). "Signal transducer and activator of transcription 3 (STAT3) is a major regulator of cell proliferation and survival, often found to be aberrantly activated in cancer." (PMID 41380973, 2025). "Through STAT3 inhibition, capsaicin can reduce the expression of immunosuppressive factors and increase cancer cell visibility to the immune system." (PMID 40808836, 2025). "Normally activated in response to stress and inflammation, STAT3 is frequently overactivated in human cancers." (PMID 39985075, 2025). "JAK3 is a significant negative regulator in cancer cell viability and apoptosis by regulating various downstream factors, such as STAT3, Akt and PS6K." (PMID 39991585, 2025). "The transcription factors STAT3 and STAT6 regulate cell functions like growth, differentiation, and immune responses, with aberrations in their activation linked to cancer, autoimmunity, and inflammation." (PMID 40309479, 2025). "Research has demonstrated that the human TSPAN8 protein regulates MYC expression by binding to its promoter, enhancing STAT3’s chromatin occupancy, and influencing cancer-related gene transcription, including MYC." (PMID 40862719, 2025). "Given its central role in orchestrating inflammation, metabolic dysregulation, and tissue catabolism, STAT3 represents a highly promising but complex therapeutic target in cancer cachexia." (PMID 40704145, 2025). "Advancements in understanding the STAT3 signaling pathway and the development of STAT3 inhibitors have underscored their potential in cancer therapy." (PMID 40166646, 2025).
cancer (continued). "Since the proposed mechanism of CTTNBP2 CRE SNV1 was to decrease a binding for a transcriptional activator, among the TFs reported by motifbreakR tool, we selected STAT3 because of its well-known role in several cancers." (PMID 39843641, 2025). "IL-24 is a member of the IL-10 cytokine family, signaling via the JAK/STAT3 signaling pathway to induce cancer cell apoptosis." (PMID 40175348, 2025). "Transfecting with a dominant active mutant of STAT3 notably counteracted CUR‐induced inhibitory effects on NCI‐H460 cells, thereby implicating STAT3 as one of the possible mechanisms by which CUR exerts its antiangiogenic effects in cancer cells." (PMID 40860906, 2025). "The activation of the Jak-Stat signaling pathway (mainly Stat3) in cancer cells increases cancer cell survival and proliferation." (PMID 40940831, 2025). "Studies have identified STAT3 as a key regulatory gene within the JAK2/STAT3 pathway, with elevated STAT3 levels observed in different cancer types." (PMID 39940837, 2025). "In several cancer types, the activity of the oncogenic STAT3 transcription factor is upregulated, which contributes to the malignancy of the disease." (PMID 40287766, 2025). "Since STAT3 serves as a convergence point for cytokine and growth factor signaling in cancer, its inhibition by pecan phenolics and metabolites provides a mechanistic explanation for the observed antiproliferative effects." (PMID 41226270, 2025). "It inhibits key cancer-related pathways, such as NF-κB, PI3K/AKT, and STAT3, thereby promoting apoptosis and reducing cancer cell proliferation." (PMID 40573993, 2025). "Endometrial CAFs secrete IL-6, which induces cancer cell proliferation through STAT-3 transcriptional activity dependent on c-Myc expression." (PMID 40136652, 2025). "These signatures are also positively correlated with proliferation and metastasis signatures, suggesting again that the redox function of APE1 and STAT3 co‐participate in regulating cellular processes in cancer." (PMID 41090323, 2025). "This review examines the phytochemical substances found in pomegranates that specifically affect STAT3 and its target genes, to explore their potential for cancer treatment." (PMID 39898127, 2025). "Curcuma longa’s curcuminoids modulate multiple cancer pathways (NF-κB, STAT3, PI3K/Akt etc.)and enhance immune responses." (PMID 41346617, 2025). "Accumulating data have shown that the transcription factor signal transducer and activator of transcription 3 (STAT3) that coordinates cancer cell survival, growth, progression, and CDDP resistance is activated in numerous types of cancer." (PMID 39859517, 2025). "STAT3 signaling plays a crucial role in cancer cell proliferation and migration, as well as influencing angiogenesis, immunosuppression and cancer stem cell (CSC) self-renewal." (PMID 40430053, 2025). "In this study, we indicate that treatment with 1 suppressed the protein level and mRNA expression level of STAT3 in three cancer cells." (PMID 40374533, 2025). "Results of this study clearly demonstrate that Pellino1 plays a key role in inflammation and inflammation-related cancer development by regulating the ubiquitination of STAT3." (PMID 39893188, 2025). "Understanding the precise role of STAT3 in different cancer types remains essential for advancing therapeutic approaches and enhancing patient outcomes." (PMID 40918170, 2025). "MDSCs in multiple cancer models overexpress cAMP signaling to activate STAT3-dependent T-cell inhibition." (PMID 40969768, 2025). "Dysregulation of STAT3 has been reported in as many as 70% of human malignancies and regulates multiple hallmarks of cancer." (PMID 41115066, 2025). "The IL-6/JAK/STAT3 pathway is aberrantly hyperactivated in many types of cancers and participates in the activation of CAFs, ultimately leading to poor clinical prognosis." (PMID 40890855, 2025).
cancer (continued). "The pathways of STAT3 are not only constitutively activated in most cancers but also play a crucial role in cellular responses to substances such as organochlorine pesticides." (PMID 40141386, 2025). "These antibodies inhibit IL‐6‐mediated signaling cascades involving JAK and STAT3 across various cancer types." (PMID 40166646, 2025). "This regulation suppresses IL-6/IL-6R/STAT3 signaling activity, leading to reduced proliferation, migration, and invasiveness of cancer cells." (PMID 41179679, 2025). "Chronic inflammation, sustained by elevated levels of IL-6 and other pro-inflammatory cytokines, perpetuates persistent activation of STAT3, establishing a self-reinforcing cycle that drives the progression of cancer cachexia." (PMID 40704145, 2025). "The aberrant activation of STAT3 has been reported in numerous cancers, including breast, lung, liver, colorectal, pancreatic, and hematological malignancies." (PMID 40075607, 2025). "In colorectal cancer, luteolin hindered migration and invasion of SW620 and SW480 cancer cells through inhibiting the STAT3 pathway." (PMID 41220717, 2025). "This mitochondrial role of STAT3, termed “mitochondrial STAT3” or mitoSTAT3, affects cellular bioenergetics, which is essential for the survival and growth of cancer cells in stressful microenvironments." (PMID 40075607, 2025). "Vinorelbine led to greater downregulation of p-STAT3 expression than STAT3 expression in cancer cells at 24 h." (PMID 40076874, 2025). "Since the JAK/STAT3 pathway is hyperactivated in many patients with cancer, JAK inhibitors have been shown in preclinical studies to inhibit the growth of many solid tumors." (PMID 40606688, 2025). "Signal Transducer and Activator of Transcription 3 (STAT3) is a promising drug target for cancer therapy." (PMID 40075607, 2025). "Using a STAT3 decoy to target activated STAT3 has been shown to inhibit cancer cell growth, induce apoptosis, and suppress STAT3‐mediated gene expression in head and HNSCC cells." (PMID 40166646, 2025). "The combination of emodin and EGFR inhibitor synergistically inhibits cancer cell proliferation in vitro and in vivo, modulating STAT3 protein expression." (PMID 40490812, 2025). "As mentioned in the previous section, IL-6 impacts cancer progression via key signaling cascades, notably the IL-6/JAK/STAT3 pathway, which plays a critical role in malignant tumor development, as well as invasion and metastasis." (PMID 40868199, 2025). "Stattic, a transcription factor involved in inflammation and cancer, is primarily known for inhibiting the activation and the phosphorylation of STAT3." (PMID 40305292, 2025). "As a crucial regulator of several proliferative pathways, miR-21 is transcriptionally regulated by the JAK2/STAT3 pathway and elevated in all human cancers." (PMID 39665584, 2025). "The following sections will examine the involvement of STAT3 in cancer progression and explore its potential as a therapeutic target, highlighting both the opportunities and challenges associated with these approaches." (PMID 40166646, 2025). "This study revealed that expression levels of STAT3 and p-STAT3 were significantly upregulated in cancer cells exposed to M2 macrophages, while they were significantly downregulated in cancer cells treated with vinorelbine." (PMID 40076874, 2025). "Despite extensive efforts to target STAT3 in cancer therapy, cancer remains a major clinical challenge, even with the advent of novel treatment strategies." (PMID 40704145, 2025). "To establish the clinical relevance of this PRL2-mediated STAT3 activation, we surveyed the TCGA cancer patient database." (PMID 39665584, 2025). "Abnormal activation of STAT1, STAT3, STAT5A, and STAT5B has been found in multiple carcinomas and cancer cell lines and linked to inflammation, invasion, metastasis, and poor prognosis." (PMID 40808640, 2025).
cancer (continued). "Targeting STAT3 and its metabolic pathways represents a promising strategy for cancer treatment, with several inhibitors currently under clinical investigation." (PMID 40860906, 2025). "STAT3 protein levels were significantly higher in cancer cells than in normal epithelial cells and were significantly reduced in cancer cells when KDM1A was knocked out using the CRISPR-Cas9 system." (PMID 40246812, 2025). "STAT3 is widely regarded as an attractive target for the development of inhibitors for the treatment of STAT3-related diseases, such as cancers, autoimmune, and inflammatory diseases." (PMID 40332429, 2025). "Our findings uncover the critical role of MSN in regulating STAT3-mediated cancer stemness via the IL-6/NF-κB signaling axis." (PMID 40696387, 2025). "More importantly, we developed a ROS‐responsive hydrogel for the localized delivery of the Nampt inhibitor FK866 and the Stat3 inhibitor C188‐9, demonstrating potent synergistic anti‐cancer effects." (PMID 40492508, 2025). "By inhibiting the VEGFR2/STAT3 pathway, LP‐R/C@AC NPs effectively suppress cancer cell proliferation and reverse immune suppression by downregulating MMP‐9 and PD‐L1 expression." (PMID 40166646, 2025). "Previous studies have reported that the pharmacological inhibition of TFF3 modulates the PI3K/AKT, MAPK, WNT, and JAK/STAT3 signaling pathways in carcinoma cells." (PMID 39920140, 2025). "PN treatment inhibited cancer cell growth by inhibiting STAT3-mediated production of Bax, Bcl-2, Bcl-xL, and cyclin D1." (PMID 38397437, 2024). "Taken together, these data support a model in PI3K-activated cancers, in which C-terminally phosphorylated p27 activates T-ISC expansion or maintenance though p27/STAT3/cJun-dependent PTPN12 loss and activation of Pyk2 and STAT3." (PMID 38886396, 2024). "Isolated studies have demonstrated that the knockout of PRMT5 in LC cells results in a decreased proliferation rate of cancer cells by disrupting the activity of the Smad7/STAT3 signaling axis." (PMID 39678513, 2024). "The IL-6/STAT3 signaling pathway, commonly activated in cancer, involves IL-6 binding to IL-6R, which activates receptor-associated JAK, leading to the phosphorylation of STAT3." (PMID 39791716, 2024). "CALB2 collaborates with hypoxia to activate iCAFs, which secrete IL6 to upregulate CALB2 expression in cancer cells via STAT3-mediated direct transcription." (PMID 39358777, 2024). "As previously stated, it has been demonstrated that allicin can inhibit STAT3, leading to various beneficial mechanisms in combating cancer." (PMID 38542956, 2024). "At present, pan-cancer analysis of STAT3 based on cancer genome databases has attracted attention, and it has been reported that STAT3 can function as a prognostic and immunological biomarker." (PMID 38834900, 2024). "Pro-inflammatory stimulation of IL-6 underlines signalling via JAK/STAT3, which promote EMT in multiple cancer types." (PMID 39348343, 2024). "As potential sources of anthocyanin, blueberry and malvidin were found to possess inhibitory effects on the JAK/STAT3 pathway, thereby impeding the proliferation of cancer cells, as confirmed in a study." (PMID 39335919, 2024). "SPNS2 promoted cancer genesis, apoptosis and migration via S1P/S1PRs pathways that activated downstream signalling such as STAT3, AKT, ERK, Ras and Rac." (PMID 39660488, 2024). "Signal transducer and activator of transcription 3 (STAT3) is related to cancer development, proliferation, and metastasis." (PMID 38834900, 2024).